KDM6B (lysine demethylase 6B)
Diseases named in the same sentence as KDM6B in open-access papers (continued):
Sharing a sentence is not in itself a finding about the gene and the disease.
glioma (19 papers, 2012 to 2025). A benign or malignant brain and spinal cord tumor that arises from glial cells (astrocytes, oligodendrocytes, ependymal cells). "For example, recent work published in Nature Cancer revealed that inhibiting KDM6B epigenetically reprograms cytokine networks, shifting macrophages from immunosuppressive to immunostimulatory phenotypes and sensitizing gliomas to PD-1 checkpoint blockade." (PMID 38259287, 2023). "Shows antitumor efficacy in several cancers, such as glioma and leukemia; effective toreduce tumor volume in mice xenograftmodels; suppresses KDM6B-mediatedproinflammatory responses in macrophages." (PMID 36975603, 2023). "For instance, KDM6B overexpression in glioma cells increases SASP gene expression, leading to tumorigenesis and tumor progression." (PMID 30634491, 2019). "Overexpression of KDM6B increases SASP gene expression in glioma cell lines." (PMID 30634491, 2019). "With the inhibition of KDM6B, GSK-J4 induces H3K27 methylation and shows potent antitumor efficacy in several cancers including glioma and leukemia, where GSK-J4 might be involved in the downregulation of cyclic-AMP response element–binding protein." (PMID 36975603, 2023).
colon carcinoma (18 papers, 2014 to 2025). "In colon cancer, vitamin D up-regulates KDM6B and causes the expression of ZEB1, ZEB2, SNAI and other metastasis-related genes." (PMID 34001062, 2021). "Vitamin D3 analogue 1,25(OH)2D3 induces KDM6B expression and interferes with Wnt/β‐catenin signaling in human colon carcinoma cells, which implies a relationship between KDM6B and Wnt/β‐catenin signaling." (PMID 34165914, 2021). "Another JmjC containing protein, KDM6B, is transcriptionally induced by vitamin D, and KDM6B mediates a subset of effects of vitamin D on colon cancer." (PMID 28536364, 2017). "Thus, it increases by a transcriptional indirect mechanism the expression of KDM6B, a histone H3 lysine 27 demethylase that mediates the induction of a highly adhesive epithelial phenotype in human colon cancer cells." (PMID 35406059, 2022). "On the contrary, the knock-down of KDM6B or the expression of an inactive KDM6B mutant in SW-480 human colon cancer cells increased the expression of SNAIL1, ZEB1, and ZEB2 EMT ATFs, and led to consecutive decreases in E-CADHERIN, CLAUDIN1, and CLAUDIN7 expressions (epithelial markers)." (PMID 34991274, 2018). "Moreover, KDM6B was under-expressed in poor differentiated tumors (mesenchymal phenotype) in a cohort of 96 colon cancer patients." (PMID 34991274, 2018). "In contrast, KDM6B knockdown promotes tumor sphere formation, increases hepatic metastasis and peritoneal dissemination in pancreatic adenocarcinoma, and enhances epithelial-mesenchymal transition and invasiveness in colon cancer cells." (PMID 28947976, 2017). "We found that 1,25(OH)2D3 upregulates the KDM6B gene by activating its promoter, and that KDM6B knockdown reduces the induction of E-cadherin and cell differentiation and the inhibition of β-catenin transcriptional activity promoted by 1,25(OH)2D3 in colon carcinoma cells." (PMID 32854355, 2020). "Accordingly, KDM6B and SNAI1 RNA expression correlate inversely in samples from human colon cancer patients." (PMID 35406059, 2022).
glioblastoma (17 papers, 2012 to 2025). The most malignant astrocytic tumor (WHO grade IV). "Increased expression of KDM6B and consequent global H3K27 demethylation have also been reported in glioblastoma tissues and glioblastoma cell lines, implicating the H3K27 demethylation in the pathogenesis of this neoplastic disorder." (PMID 35915507, 2022).
hepatocellular carcinoma (17 papers, 2016 to 2025). A malignant tumor that arises from hepatocytes. "The depletion of KDM6B reduced the stemness of hepatocellular cancer cells, and JIB-04, a KDM4/6 inhibitor, significantly reduced the level of expression of stem cell marker genes (CD133/PROM1, CD44, LGR5, EpCAM)." (PMID 40940894, 2025). "For example, KDM6B acts as a critical driver of hepatocellular carcinoma stem cell‐like and metastatic behaviors." (PMID 34165914, 2021). "High expression of KDM6B is correlated with distant metastasis via modulating H3K27me3 of SLUG gene promoter in hepatocellular carcinomas." (PMID 34950587, 2021). "For example, in hepatocellular carcinomas, tissue-based RT-qPCR and Western-blotting analysis showed that KDM6B was overexpressed in tumor tissues compared to normal adjacent tissues." (PMID 34991274, 2018). "Among these genes are TPM3, which is frequently overexpressed in human hepatocellular carcinoma, and the histone demethylase KDM6B, both of which may be involved in the epithelial–mesenchymal transition in hepatocarcinogenesis." (PMID 35557512, 2022). "Collectively, our results suggest that JIB-04-mediated targeting of histone demethylases, such as KDM4B, KDM4D, and KDM6B, inhibits the malignancy of hepatocellular carcinoma via growth inhibition and cell cycle arrest and, in addition, affects the maintenance and viability of liver CSCs." (PMID 35887001, 2022). "In addition, KDM6B has been shown to be overexpressed in gastric cancer, hepatocellular carcinoma and lymphoma and promote their survival and progression." (PMID 34165914, 2021). "Interestingly, higher KDM6B expression also acted as a predictor for recurrence in some other common cancers, including hepatocellular carcinoma, lung adenocarcinoma, pancreatic cancer, and bladder cancer." (PMID 32929331, 2020). "However, KDM6B expression has also been correlated with metastasis in clear cell renal cell carcinoma, ovarian cancer, myeloma, hepatocellular carcinoma, malignant pleural mesothelioma, and Hodgkin’s lymphoma or invasive breast tumors." (PMID 33291363, 2020). "Additionally, we found a low basic KDM6B gene expression in HepG2 cells compared to PHH that is in line with findings in various cancers, including liver carcinoma." (PMID 30654452, 2019). "Transfection of pre-miR-941 into the neutrophil promyelocyte cell line PLB-985 cells did not result in reduction of the KDM6B mRNA level in a hepatocellular carcinoma cell line." (PMID 27755585, 2016). "KDM6B could promote the invasion of hepatocellular cancer, non-small cell lung cancer, renal cell cancer and chordoma through upregulation of EMT-specific genes, such as TIAM1, E-cadherin, SNAI1 and TBXT." (PMID 34950587, 2021).
leukemia (15 papers, 2018 to 2025). A malignant (clonal) hematologic disorder, involving hematopoietic stem cells and characterized by the presence of primitive or atypical myeloid or lymphoid cells in the bone marrow and the blood. "To gain insight into the impact of KDM6B overexpression in truncated ASXL1–associated leukemia development, we generated two KDM6B knockout clones in K562 cells using the CRISPR/Cas9 system." (PMID 37917239, 2024). "Pharmacologic KDM6B inhibition blocks the growth of ASXL1-mutated leukemia cells." (PMID 37917239, 2024). "We also examined the impact of GSK-J4 on the cell growth of several other leukemia cell lines with lower expression of KDM6B, including OCI-AML3, THP-1, and MOLM-13 cells." (PMID 37917239, 2024). "The EVI1/KDM6B/H3K27me3/LAPTM4B signaling pathway was also identified in EVI1hi human leukemia cell lines." (PMID 39680456, 2024). "We next performed Western blots to assess the protein levels of KDM6B in two leukemia cell lines, Kasumi-1 and K562 cells with ASXL1 truncating mutations as ASXL1 G646WfsX12 and ASXL1 Y591X, respectively." (PMID 37917239, 2024). "A previous study suggested that the NIPBL protein interacts with KDM6B in leukemia cells." (PMID 38378967, 2024). "Kdm6b loss in mice has been shown to impair HSC self-renewal and enhance HSC differentiation, and Kdm6a-deficient mice have been shown to exhibit abnormal differentiation with myeloid skewing, impaired hematopoietic reconstituting ability, and increased susceptibility to leukemia." (PMID 37917239, 2024). "Additionally, we have demonstrated that pharmacologic inhibition of KDM6B in Asxl1-mutant HSPCs restores H3K27me3 level, normalizes leukemogenic gene expression and HSPC function, and reduces the tumor burden in mouse models of ASXL1 mutation–mediated leukemia." (PMID 37917239, 2024). "Transcriptional analysis showed that heterozygous deletion of Kdm6b in Asxl1Y588XTg normalizes the majority of upregulated genes critical for HSC function and leukemia development, correlating with restored H3K27me3 levels." (PMID 37917239, 2024). "We observed upregulation of both KDM6B and LAPTM4B in EVI1hi leukemia cells compared with EVI1lo leukemia cells." (PMID 39680456, 2024). "Moreover, KDM6B inhibitor and LAPTM4B knockdown significantly inhibited growth and induced apoptosis of EVI1hi leukemia cell lines." (PMID 39680456, 2024).
colorectal cancer (14 papers, 2018 to 2025). A primary or metastatic malignant neoplasm that affects the colon or rectum. "In colorectal cancer, high KDM6B expression predicted good prognosis, and knock-down of KDM6B was associated with augmented cell proliferation and inhibited apoptosis." (PMID 31036064, 2019). "Lysine-specific demethylase 6B (KDM6B) plays a suppressive or oncogenic role in colorectal cancer (CRC)." (PMID 40959109, 2025). "In vitro, these bacteria were co-cultured with colorectal cancer cells and KDM6B-overexpressing colorectal cancer cells to test their effect on KDM6B inhibition and DKK2 expression." (PMID 40340623, 2025). "To investigate the role of KDM6B in colorectal cancer cells, we constructed a stable overexpression vector for KDM6B in the human CRC cell line HCT116 and mouse CRC cell line CT26." (PMID 40959109, 2025). "In colorectal cancer and melanoma, KDM6B expression is elevated and positively correlated with several targets of CXCL9, CXCL10, STC1 and CCL2, which affects the tumor immune microenvironment by T cells and macrophage infiltration." (PMID 34950587, 2021). "Low expression of KDM6B is an independent predictor of poor prognosis in colorectal cancer by mediating p15INK4B expression." (PMID 34950587, 2021). "In 20 colorectal cancer patients, KDM6B was also under-expressed compared to normal tissues, and a high KDM6B expression was correlated with better overall survival in a cohort of 151 colorectal cancer (CRC) patients." (PMID 34991274, 2018).
melanoma (13 papers, 2018 to 2025). A malignant, usually aggressive tumor composed of atypical, neoplastic melanocytes. "The highest frequency of change in KDM6B (>8%) was found in melanoma patients with “mutation” as the main type." (PMID 35783266, 2022). "Moreover, a KDM6B deficiency with a subsequent H3K27me3 enrichment promoted the dedifferentiation of hypoxicV600E BRAF melanoma cells and then led to BRAF inhibitor resistance." (PMID 33414463, 2021). "Our analysis of publicly available Talantov melanoma datasets revealed that only EZH2, BRD7/9, BRD2/3/4, BRPF1, EHMT2, and KDM6B were significantly overexpressed at the mRNA level in patient melanoma tissue samples as compared to the normal skin samples." (PMID 34771678, 2021). "Depletion of KDM6B in melanoma induces self-renewal, invasive migration, metastasis and angiogenesis." (PMID 33003334, 2020). "KDM6B could activate NF-kB and bone morphogenic protein signaling promoting melanoma growth and progression." (PMID 34220955, 2021). "KDM6B was found to be essential for melanoma tumor growth and metastasis." (PMID 34220955, 2021). "On the other hand, KDM6B appears to act as an oncogene in melanoma and B-cell lymphoma." (PMID 33003334, 2020). "The results of immunohistochemistry analyses of melanoma tissues from the Human Protein Atlas indicated that BRD7, BRD9, BRD4, BRD3, and KDM6B were mostly expressed at >75% level." (PMID 34771678, 2021). "Indeed, the authors identified a novel epigenetic mechanism by which KDM6B transcriptionally upregulates several targets of NF-κB and BMP (Bone Morphogenic Protein) signaling to promote melanoma progression and metastasis." (PMID 32042336, 2020). "KDM6B, BRD2, and BRD3 were moderately to weakly expressed in melanoma samples, whereas weak staining intensity was observed for BRPF1 and EHMT2 in melanoma samples as compared with normal skin tissue indicating that they are significantly expressed at low levels in melanoma samples." (PMID 34771678, 2021).
prostate carcinoma (13 papers, 2012 to 2025). A carcinoma that arises from epithelial cells of the prostate gland. "In the current study, we used an H3K27 demethylase (JMJD3/KDM6B) inhibitor to study its effects on TGFβ-induced EMT in prostate cancer cells." (PMID 36768182, 2023). "KDM6B was also found to promote tumorigenesis in prostate cancer cells by inducing transcription of cyclin D1 and knocking it out was shown to have anti-cancer effects." (PMID 36768182, 2023). "KDM6B expression is also upregulated in prostate cancer (PCa) and is further increased during metastasis." (PMID 33414463, 2021). "Overexpression of KDM6B exerts an anti-apoptotic effect in diffuse large B-cell lymphoma and prostate cancer, and respectively activates the transcription of downstream target genes IRF4 and PTEN via distinct mechanisms." (PMID 34950587, 2021). "Therefore, we used GSK-J4, a histone H3K27 demethylase (JMJD3/KDM6B) inhibitor, to increase the H3K27me3 levels to check if it leads to prostate cancer progression inhibition." (PMID 36768182, 2023). "Thanks to the growing studies of KDM6B, GSK-J4 has been applied to different kinds of tumors such as T-ALL, diffuse large B-cell lymphoma, pediatric brainstem glioma and prostate cancer with dismal toxicity for normal hematopoietic progenitor cells." (PMID 29594337, 2018). "In support of our data, neuroblastoma is the third most sensitive among 25 different cancer lineages that are sensitive to knockdown of KDM6B but not KDM6A, just below prostate cancer and myeloma, in a genome-wide shRNA screen (20 shRNAs per gene) in 709 cancer cell lines (DepMap dataset)." (PMID 34893606, 2021).
acute myeloid leukemia (12 papers, 2018 to 2024). Acute myeloid leukemia (AML) is a group of neoplasms arising from precursor cells committed to the myeloid cell-line differentiation. "Studies have shown that abnormal levels of the histone demethylases lysine demethylase 6A (KDM6A) and KDM6B are associated with pediatric acute myeloid leukemia (AML)." (PMID 36081552, 2022). "Studies have shown that abnormal levels of the histone demethylases, KDM6A and KDM6B, are associated with pediatric acute myeloid leukemia (AML)." (PMID 34765551, 2021). "Genetic alteration of KDM6B also affected the prognosis of acute myeloid leukemia (LAML) and testicular germ cell tumors (TGCTs)." (PMID 35783266, 2022). "KDM6B expressional reduction is found in acute myeloid leukemia, and KDM6B acts as an oncorepressor by activating C/EBPβ-centered transcriptional program." (PMID 34950587, 2021). "In acute myeloid leukemia (AML) KDM6B is upregulated and correlated with poor prognosis." (PMID 33003334, 2020). "In acute myeloid leukemia (AML), particularly the M2 and M3 subtypes, KDM6B overexpression reduces the number of leukemia stem cells, promotes bone marrow differentiation, and induces cellular senescence by upregulating the expression of C/EBPβ and its target genes." (PMID 39620228, 2024). "KDM6B is overexpressed in Hodgkin’s lymphomas (HLs), diffuse large B-cell lymphoma (DLBCL), acute myeloid leukemia (AML), and MM." (PMID 37566089, 2023). "In contrast, KDM6B overexpression has been observed in Hodgkin’s lymphomas (HLs), DLBCL, Multiple myeloma (MM) and Acute myeloid leukemia (AML)." (PMID 34200679, 2021).
lung carcinoma (12 papers, 2020 to 2025). "We showed that lung cancer patients presenting high EZH2 mRNA levels or high KDM6B mRNA levels presented a significantly higher risk of early death (p = 3.4 ×10−5 and p = 4.8 × 10−5) compared to patients with lower EZH2 or KDM6B mRNA levels." (PMID 33291363, 2020). "We recently demonstrated that oncogenic Ras induces syntenin-1 expression in human lung cancer cells by activating KDM6B histone K3H27 demethylase." (PMID 35136055, 2022). "On the contrary, high KDM6B expressions were related to poor OS (p = 5.3e-05) and FP (p = 8.3e-11) prognosis for lung cancer and poor OS (p = 1.3e-10), FP (P = 1e-09) and PPS (p < 1.0e-16) prognosis for gastric cancer." (PMID 35783266, 2022). "Specific targets, such as PRMT1, KDM6B, CARM1, BRD4, and EZH2, have been shown to be associated with malignant phenotypes of lung cancer, influencing cell proliferation and metastatic processes (regulation of epithelial–mesenchymal transition and cell invasion)." (PMID 36233212, 2022). "We performed Co-IPs to determine whether NIPBL similarly interacts with KDM6B in lung cancer cells." (PMID 38378967, 2024). "Here, we demonstrate that Jumonji domain containing-3 (JMJD3 also called KDM6B) promotes TGF-β-mediated Smad activation and EMT in Ras-activated lung cancer cells." (PMID 33637682, 2021). "Using nontoxic doses of the remaining inhibitors, KDM6B and PADI4 were identified as potential targets affecting the invasion and migration of metastatic lung cancer cell lines." (PMID 36233212, 2022).
T-cell acute lymphoblastic leukemia (12 papers, 2015 to 2024). Acute lymphoblastic leukemia of T-cell origin. "A previous study highlighted KDM6B’s crucial role in supporting NOTCH1-driven T cell acute lymphoblastic leukemia." (PMID 38566223, 2024). "It has been reported that KDM6B is highly expressed in T cell acute lymphoblastic leukemia (T-ALL) and is essential for its initiation and maintenance." (PMID 29594337, 2018). "Although other JmjC KDM subfamilies members are supposed to involve in tumoringenesis, for example KDM6B in T-cell acute lymphoblastic leukemia (T-ALL), reports of their roles in lung cancer are very limited." (PMID 30002791, 2018). "KDM6B is overexpressed in a variety of blood disorders, including myelodysplastic syndromes, M5 acute myeloid leukemia, Hodgkin’s lymphoma, multiple myeloma, and T cell acute lymphoblastic leukemia." (PMID 39680456, 2024). "In this regard, opposite functions of KDM6B and KDM6A have been demonstrated in the T-cell acute lymphoblastic leukaemia (T-ALL), being KDM6B essential to initiate and maintain these tumors, whereas KDM6A acts as a tumour suppressor, being frequently genetically inactivated." (PMID 26580594, 2015). "However, this gene overexpression was detected in various blood disorders, including myelodysplastic syndromes (MDS), Hodgkin’s lymphoma (HL), multiple myeloma (MM) and T-cell acute lymphoblastic leukemia (T-ALL), implying the need to inhibit KDM6B for successful cancer therapy." (PMID 35681732, 2022).